FST (follistatin)
Diseases named in the same sentence as FST in open-access papers (continued):
Sharing a sentence is not in itself a finding about the gene and the disease.
Insulin resistance (continued). "Mice with liver-specific overexpression of follistatin exhibited increased hepatic glucose production, as well as aggravated insulin resistance in adipose tissue and skeletal muscle accompanying whole-body glucose intolerance, while follistatin knockdown improved insulin sensitivity." (PMID 34944728, 2021). "Abnormally elevated follistatin secretion may further exacerbate liver insulin resistance by promoting FFA production from adipose tissue and ultimately lead to NAFLD, possibly aggravating diabetes." (PMID 34759311, 2021). "Based on our findings, this phenomenon may now be explained by the fact that the GCKR-GCK disruptor may have increased liver cell follistatin secretion, which in turn, may have promoted adipose tissue insulin resistance and an increase of triglyceride levels." (PMID 34759311, 2021). "Among the mechanisms that may explain this relationship in humans we found supporting evidence that follistatin induces insulin resistance in adipose tissue, thereby, promoting adipose tissue lipolysis and NAFLD." (PMID 34759311, 2021). "High circulating follistatin associates with adipose tissue insulin resistance and non-alcoholic fatty liver disease (n = 210, Germany)." (PMID 34759311, 2021). "A possible mechanism may involve an effect of follistatin to induce adipose tissue insulin resistance, resulting in increased adipocyte free fatty acid (FFA) release, which also promotes nonalcoholic fatty liver disease (NAFLD)." (PMID 34759311, 2021). "Notably, follistatin is correlated with insulin resistance in patients with polycystic ovary syndrome." (PMID 23304117, 2012). "Clinically, activin A, B, or follistatin may be useful as indicators of the severity of T2D and insulin resistance." (PMID 23304117, 2012). "Furthermore, it needs to be established whether and to what extent genetics explains the variability of circulating follistatin levels and whether the mechanisms of follistatin to induce insulin resistance in mice may also be operative in humans." (PMID 34759311, 2021). "Considering the implication of the Activin-Follistatin system in glucose and lipid metabolism, key elements in insulin resistance developed during pregnancy, we hypothesized that serum levels of activin A, follistatin and FSTL3 would be associated with pregnancies affected by GDM." (PMID 24763182, 2014). "Among these hepatokines are fetuin A, follistatin, HFREP1, LECT2, PEDF, and ectodysplasin, collectively exacerbating insulin resistance in skeletal muscle and adipose tissue through the activation of the c-Jun N-terminal kinase signaling pathway." (PMID 40704318, 2025). "There are data that confirm the impact of conditions such as insulin resistance, chronic inflammation, cirrhosis, or arteriosclerosis on the increased production of MSTN antagonists such as irisin, follistatin, or IGF-1." (PMID 38542721, 2024). "However, circulating follistatin was elevated in patients with DM2 and generally correlates with insulin resistance markers, such as fasting glucose, glycated hemoglobin, and 2-h glucose during an oral glucose tolerance test." (PMID 33807959, 2021). "Higher levels of follistatin and resistin are associated with the lack of pre-ovular follicle development in PCOS or insulin resistance." (PMID 33740002, 2021). "The fact that serum levels of activins or follistatin are not clearly predictive of T2D or insulin resistance in individual patients could be due to the complicated roles of activin A and B in the regulation of glucose and insulin metabolism." (PMID 23304117, 2012).
sarcopenia (17 papers, 2015 to 2026). Progressive decline in muscle mass due to aging which results in decreased functional capacity of muscles. "Changes in myostatin, IGF-1, follistatin, and creatine kinase levels have been shown to be linked with COVID-19-related sarcopenia." (PMID 40943488, 2025). "The biological process underlying sarcopenia is unclear, but the proteins myostatin and follistatin are involved in the balance between muscle breakdown and synthesis." (PMID 39585121, 2024). "Follistatin, on the other hand, was positively associated with frailty and sarcopenia." (PMID 39585121, 2024). "After adjusting for age, oxytocin (odds ratio (OR) 0.75; 95% confidence intervals (CI) 0.63–0.98; p = 0.019) was associated with osteoporosis, and DHEA (OR 0.73; 95% CI 0.51–0.96; p = 0.032) and follistatin (OR 1.66; 95% CI 1.19–3.57; p = 0.022) were associated with sarcopenia." (PMID 34641817, 2021). "However, circulating FST levels are negatively associated with muscle mass, strength, and function in older women, suggesting that FST may be used as a biomarker of sarcopenia." (PMID 40171198, 2025). "However, follistatin reduces the number of ROS, whereas a deficiency of follistatin may lead to oxidative stress and result in numerous diseases, including sarcopenia and NAFLD." (PMID 34680417, 2021). "However, elevated follistatin levels were associated with an increased risk of sarcopenia." (PMID 34641817, 2021). "Studies have shown that increased expression of follistatin can significantly enhance muscle repair and regeneration capacity, slowing the progression of sarcopenia." (PMID 41140691, 2025). "This interaction between environmental and genetic factors reveals the potential value of follistatin in the treatment of sarcopenia, providing new perspectives for the application of personalized medicine." (PMID 41140691, 2025). "A study in older adults with sarcopenia showed that follistatin levels increased with 16 weeks of resistance exercise." (PMID 39895162, 2025). "Due to its implications in the human quality of life, most of the studies about sarcopenia and frailty with myostatin or follistatin have been developed in human serum/plasma." (PMID 39585121, 2024). "There is experimental evidence on the role of carnitine insufficiency in patients with sarcopenia and heart failure or the impact of follistatin on muscle mass in mice is suggested." (PMID 38674917, 2024). "In the case of follistatin, the obtained pattern was just the opposite: firstly, it is low, then it increases, and then it reduces again with severe sarcopenia (basal–up–down)." (PMID 39585121, 2024). "Studies realized on aged human serums and our results on C2C12 murine cells show a similar tendency, where myostatin is downregulated and follistatin is upregulated in severe sarcopenia." (PMID 39585121, 2024). "Using myostatin and/or follistatin as sarcopenia biomarkers requires further knowledge of the way they evolve alongside muscle aging." (PMID 39585121, 2024). "We analyzed cellular morphological changes alongside the aging process, as well as the protein and gene expression of molecules related to sarcopenia, such as myostatin and follistatin." (PMID 39585121, 2024). "In this paper, we address the role of myostatin and follistatin as potential markers in the diagnosis of sarcopenia in patients with Crohn’s disease and ulcerative colitis, particularly in view of the genetic and biological aspects." (PMID 34680417, 2021). "Nevertheless, knowledge is still scarce about the roles of follistatin and myostatin in sarcopenia development among patients suffering from inflammatory bowel disease, which warrants further study." (PMID 34680417, 2021). "Additionally, alterations in myostatin, insulin-like growth factor 1 (IGF-1), follistatin, and creatine kinase point to significant muscle involvement, consistent with sarcopenia, weakness, and functional decline in post–COVID-19 patients." (PMID 41439932, 2025).
sarcopenia (continued). "Therefore, enhancing the expression or activity of follistatin is considered a promising strategy for the treatment of sarcopenia." (PMID 41140691, 2025). "The gene expressions of myostatin and follistatin along the sarcopenia model, as in the analysis of protein expression, showed an opposite profile for both molecules: an inverted U-shape for myostatin (basal–up–down) and a U-shape for follistatin (basal–down–up)." (PMID 39585121, 2024). "Even if the biological process underlying sarcopenia is not very clear, it is known that myostatin and follistatin are implicated in the balance between the synthesis and degradation of skeletal muscle." (PMID 39585121, 2024). "Protein and gene expressions of myostatin and follistatin were analyzed along the sarcopenia model." (PMID 39585121, 2024). "Another important factor in the development of sarcopenia is an imbalanced ratio of myostatin and follistatin, which may stem from inflammation as well as genetic factors." (PMID 34680417, 2021). "Notably, our results showed that excluding the influence of vitamin D, oxytocin was also associated with osteoporosis, and follistatin and DHEA were associated with sarcopenia." (PMID 34641817, 2021). "However, our results also showed that follistatin and DHEA were associated with sarcopenia, excluding the influence of exercise." (PMID 34641817, 2021). "Therefore, serum DHEA and follistatin may be biomarkers of sarcopenia, and serum oxytocin may be a biomarker of osteoporosis." (PMID 34641817, 2021). "For instance, the downregulated level of irisin and follistatin or the upregulation of activin A, TGF-β, and myostatin indicates a decrease in muscle mass and thus can serve as the biomarker for diagnosing sarcopenia." (PMID 37815907, 2024). "A recent Korean study of 238 HCC patients reported that the serum level of several myokines including follistatin and IL-6 was higher in HCC patients with sarcopenia than in heathy controls, and that it was related to poor survival." (PMID 35538112, 2022). "We observed that postmenopausal women with sarcopenia were more likely to have lower DHEA levels and higher follistatin levels, and postmenopausal women with osteoporosis were more likely to have lower oxytocin levels." (PMID 34641817, 2021). "Postmenopausal women with sarcopenia were more likely to have lower DHEA levels and higher follistatin levels, and postmenopausal women with osteoporosis were more likely to have lower oxytocin levels." (PMID 34641817, 2021). "The main strength of the current study was that it simultaneously considered the relationship between several biomarkers, including myostatin, follistatin, oxytocin, BDNF, DHEA, T2 and E2, and osteoporosis and/or sarcopenia in the same study population." (PMID 34641817, 2021). "Another study found that while the concentration of myostatin was lower in people with frailty or sarcopenia, the level of follistatin was higher in people with frailty, so a negative association was observed between myostatin and frailty, and sarcopenia." (PMID 39585121, 2024). "For series 1, the group agreed on 4 biochemical markers that should be assessed in Phase II or Phase III trials (i.e., Myostatin-Follistatin, Brain Derived Neurotrophic Factor, N-terminal Type III Procollagen and Serum Creatinine to Serum Cystatin C Ratio – or the Sarcopenia Index)." (PMID 36633611, 2023). "Notably, the correlations between serum follistatin and DHEA and sarcopenia and the correlation between serum oxytocin and osteoporosis were independent of exercise and vitamin D levels." (PMID 34641817, 2021). "Another study also reported that serum levels of follistatin were not different among young males, older men with mild sarcopenia, and older men with severe sarcopenia." (PMID 32927586, 2020). "However, they failed to correlate the increased follistatin concentration with sarcopenia defined according to the revised European consensus." (PMID 38674917, 2024).
sarcopenia (continued). "DHEA (32.51 ± 12.8 and 34.97 ± 16.2 vs. 42.64 ± 12.8 and 48.45 ± 10.6, p = 0.042) was significantly lower, and follistatin (18.76 ± 4.8 and 18.97 ± 6.1 vs. 14.93 ± 4.0 and 13.0 ± 4.9, p = 0.027) was significantly higher in the sarcopenia group than the respective levels in nonsarcopenia group." (PMID 34641817, 2021). "Therefore, serum oxytocin, DHEA and follistatin are promising candidates as serum biomarkers related to osteoporosis and/or sarcopenia, regardless of exercise and vitamin D status." (PMID 34641817, 2021). "Recently, studies have introduced muscle-related biomarkers, including growth differentiation factor-15 (GDF-15), GDF-8 (myostatin), activin A, and follistatin that could be used as identifiable markers of sarcopenia, but a lack of studies may limit the confirmation of predictable biomarkers." (PMID 32927586, 2020).
type 2 diabetes (13 papers, 2014 to 2025). "Higher follistatin levels have been associated with an increased risk for type 2 diabetes and with polycystic ovary syndrome (PCOS)." (PMID 36843579, 2023). "In humans, follistatin derives mainly from the liver and augmented follistatin levels have been associated with an increased risk for type 2 diabetes, independently of established risk markers." (PMID 36843579, 2023). "A recent report by Wu and colleagues found out that elevated circulating follistatin concentrations were associated with an increased risk of type 2 diabetes." (PMID 36294318, 2022). "Follistatin promotes in type 2 diabetes (T2D) pathogenesis in model animals and is elevated in patients with T2D." (PMID 34759311, 2021). "On the other hand, elevated follistatin correlates with the incidence of type 2 diabetes." (PMID 41198895, 2025). "Also important is the increased concentration of follistatin, which is associated not only with PCOS, but also with other diseases that may co-occur with PCOS, such as type II diabetes." (PMID 39415788, 2024). "The hepatokine follistatin is elevated in patients with type 2 diabetes (T2D) and promotes hyperglycemia in mice." (PMID 34759311, 2021). "The serum follistatin level is increased in patients with NAFLD and type 2 diabetes, while individuals with reduced body weight after bariatric surgery exhibited a decrease in serum follistatin level, in conjunction with improved insulin sensitivity and glycemic control." (PMID 34944728, 2021). "Following reports that higher levels of follistatin are associated with an increased risk of type 2 diabetes and PCOS, a paper presented in Frontiers in Endocrinology investigated the effects of treatment of non-obese adolescent girls with PCOS on follistatin concentrations." (PMID 39415788, 2024). "Finally, early reduction of circulating follistatin after bariatric surgery predicts the improvement in insulin sensitivity observed later in morbidly obese individuals with and without type 2 diabetes." (PMID 31672146, 2019). "Aim of our study was to investigate whether high dose (3 mg) short-term (5 weeks) treatment with liraglutide in obese patients with no overt type 2 diabetes affects metabolites, lipid and lipoprotein profile and components of activin–follistatin axis in cardiovascular beneficial or detrimental way." (PMID 31672146, 2019).
lung carcinoma (12 papers, 2010 to 2025). "Taken together, these results suggested that expression of serum FST seemed likely to have a potential diagnostic value in patients with lung cancer." (PMID 30377409, 2018). "We firstly investigated the association between serum FST expression and the patients with lung cancer." (PMID 30377409, 2018). "Therefore, determination of serum FST levels not only can be used in the auxiliary clinical diagnosis of lung cancer but also might be associated with tumor progression and metastasis." (PMID 30377409, 2018). "However, it remains unclear whether serum FST expression is associated with lung cancer patients with different histological types, TNM staging, tumor progression, and recurrence." (PMID 30377409, 2018). "Beyond estrogens and androgens, there is limited data on leptins and the activin-binding protein follistatin in the efficacy of PD-1/PD-L1 in lung cancer therapy." (PMID 41463203, 2025). "In our study we also found the downregulation of both TEAD2 and FST genes, in lung cancer cells after Bcl-2 silencing." (PMID 38755629, 2024). "Microarray analysis revealed a 21-fold increase in FST expression in lung carcinoma cells following direct contact with fibroblasts, highlighting a role of fibroblasts or fibroblast-secreted factors in the regulation of FST in cancer epithelial cells." (PMID 38392348, 2024). "Among the top five factors secreted by CAFs in lung cancer, FST surprisingly emerged as a critical player in rescuing cancer cells from EGFR-TKI-induced toxicity, and thus represents a potential target to combat drug resistance in NSCLC." (PMID 38392348, 2024). "Recombinant ActA promotes lung cancer cell proliferation in vitro, and treatment with follistatin, an antagonist of ActA, significantly inhibits tumor formation in vivo." (PMID 38720352, 2024). "It has already been reported that serum levels of ActA and its inhibitor follistatin increased in lung cancer patients in a stage-dependent manner." (PMID 38720352, 2024). "Serum FST levels was found higher in lung cancer patients respect to healthy subjects and in patients with lung benign disease, while TEAD2 targeting was responsible of cisplatin sensitization in NSCLC." (PMID 38755629, 2024). "Accordingly, follistatin, an antagonist of activin A is able to inhibit lung cancer cell proliferation." (PMID 36650150, 2023). "In our study, we investigated the relationship between serum FST levels and lung cancer with histologic types, TNM staging, and recurrence." (PMID 30377409, 2018). "We found that serum FST levels in patients with lung cancer were significantly higher as compared to HSs (P < 0.0001) and BLD (P < 0.001)." (PMID 30377409, 2018). "In summary, a significant increase of serum FST levels in the patients with lung cancer and those with recurrent lung cancer is closely related to the clinical staging of tumors." (PMID 30377409, 2018). "ROC analysis revealed that when compared LC with HSs and BLD, the serum FST levels provided a diagnosis efficacy with AUC of 0.971 and 0.728 respectively, indicating that serum FST seemed likely to have a potential role in lung cancer diagnosis." (PMID 30377409, 2018). "In this study, we firstly examined serum FST levels in lung cancer patients with different histological types." (PMID 30377409, 2018). "We next calculated the sensitivity and specificity of serum FST level in patients with different histological types of lung cancer using 1509.55 pg/mL and 970.74 pg/mL as the cut-off value respectively." (PMID 30377409, 2018). "In search of lung cancer markers, we found that serum FST levels were elevated in some patients of lung adenocarcinoma." (PMID 25347573, 2014). "We examined serum FST in patients with lung cancers in different histological backgrounds, including adenocarcinoma, squamous carcinoma, small cell lung carcinoma." (PMID 25347573, 2014).
lung carcinoma (continued). "Analysis of The Cancer Genome Atlas (TCGA) datasets revealed that FSTL3 was associated with poor survival outcomes in multiple cancers, including ovarian, colorectal, pancreatic and lung cancers; in comparison, FST had a weaker correlation of poor prognosis for ovarian cancer." (PMID 41029436, 2025). "Since follistatin, an activin A inhibitor, significantly blocked tumor progression in vivo, we can reasonably assume that new lines of therapies targeting lung AMs in tumors will become a promising approach for eradicating lung cancers in the future." (PMID 36650150, 2023). "Finally, serum FST levels were evaluated in patients with recurrent lung cancer." (PMID 30377409, 2018). "Specifically, lung cancer cell lines transfected with follistatin and injected into immunodeficient mice markedly inhibited metastasis compared with non-transfected cell lines, but the authors of the study recognize that the role of follistatin in cancer metastasis is totally unknown." (PMID 21047417, 2010). "Since LADC is the most common histological type of lung cancer with a classical TNM staging, we further evaluated serum FST expression in patients with LADC according to the TNM staging." (PMID 30377409, 2018).